IL6 (interleukin 6)
Diseases named in the same sentence as IL6 in open-access papers (continued):
Sharing a sentence is not in itself a finding about the gene and the disease.
malaria (continued). "Interestingly, a higher ratio of IL-6 to IL-10 was also observed in sera of Vietnamese patients with fatal severe malaria, vs. those with severe disease who survived, implicating unbalanced pro-inflammatory and anti-inflammatory cytokine production as a risk factor for fatal malaria." (PMID 20591122, 2010). "Proinflammatory cytokines such as TNF-α, IL-1, and IL-6, which are upregulated during malaria, increase HIV proviral expression through the provirus modulatory enhancer region." (PMID 19774084, 2009). "In an adult population in a malaria-endemic region of India, high levels of IL-12, IL-5, and IL-6 discriminated severe forms of malaria from mild malaria." (PMID 19680452, 2009). "The defense/immune response interactome is structured around three hubs of high interconnectivity–TNF, IFN-γ and IL-6, all of which play significant roles in host pro-inflammatory responses to malaria." (PMID 18483551, 2008). "Previously, malaria-induced lethality in mice infected with P. chabaudi has been shown to be overcome by interrupting the alternative IL-6 trans-signaling pathway mediated by IL-6 bound to the soluble (s)IL-6Rα." (PMID 40243929, 2025). "IL-6 is also known to play a critical role in the course and outcome of blood-stage malaria." (PMID 40243929, 2025). "Thus, an excessive inflammatory response mediated by cytokines like TNF, IL-1, and IL-6 likely contributes to the tissue damage and organ dysfunction observed in severe malaria and typhoid fever." (PMID 40014608, 2025). "Furthermore, elevated serum IL-6 levels in malaria patients positively correlate with anemia severity." (PMID 40980010, 2025). "In the malaria and typhoid fever co-morbidity group, a positive correlation was recoded between IL-2/TNFα (r = 0.515, p = 0.03), IL-2/IL-6 (r = 0.536, p = 0.02) and IL-6/TNF-α (r = 0.664, p = 0.007)." (PMID 40014608, 2025). "Additionally, there was a positive correlation between perceived stress scores and IL-2 (r = 0.365, p = 0.002), IFN-γ (r = 0.248, p = 0.03), and IL-6 (r = 0.412, p = 0.0001) in the typho-malaria group." (PMID 40014608, 2025). "Additionally, the levels of the peripheral cytokines IL-6 and IL-10 were elevated in infected women, which were correlated with previous maternal exposure to malaria, increased parasitemia, and reduced maternal weight gain and the gestational age at delivery." (PMID 39495782, 2024). "•Animal data suggest interleukin-6 (IL-6) signaling has a role in malaria." (PMID 36801374, 2023). "Furthermore, in both types of malaria (severe and uncomplicated), Gal-9 levels were associated with various pro- and anti-inflammatory cytokines and chemokines, including TNF, IL-6, IFN-α2, IFN-γ, IL-1Ra, and IL-10." (PMID 38067100, 2023). "The engaged immune cells release inflammatory factors, such as pro-inflammatory cytokines/chemokines (e.g. IL-1β, TNF-α, Il-12, IL-10, Il-6), nitric oxide (NO) and reactive oxygen species (ROS) that drive the inflammatory response and lead to the fever-like symptoms observed in malaria patients." (PMID 37350957, 2023). "This work leaves several questions about the role of IL-6 in severe malaria." (PMID 36801374, 2023). "These analyses do not support a causal role for IL-6 signaling in the development of severe malaria." (PMID 36801374, 2023). "However, we would caution overinterpretation of our null result to suggest that IL-6 is irrelevant in severe malaria; although, it does weaken the case for suggestion of IL-6 inhibition as a therapeutic option." (PMID 36801374, 2023). "Increased levels of IL-6 have been demonstrated both during canine babesiosis and human malaria." (PMID 36839438, 2023). "Moreover, increases in the IL-6/IL-10 ratio have been reported to be a predictor of death in patients with malaria." (PMID 36668942, 2023).
malaria (continued). "Here, we observed that IL-10 and IL-6 levels were 1.3- to 18.0-fold lower in those with malaria-intestinal parasite co-infections (both helminths and protozoa) than in those with plasmodial mono-infections, although they were still higher than those in uninfected participants." (PMID 35421083, 2022). "Interestingly, co-infected malaria patients showed IL-6 serum levels decreased compared to individuals only infected with P. vivax." (PMID 35749690, 2022). "Our meta-analysis of the pooled evidence might suggest better analysis of measurements of IL-6 during malaria infections in future studies to monitor malaria severity." (PMID 35396564, 2022). "Serum levels of sTREM-1 and IL-6 were measured in patients with malaria and controls." (PMID 35749690, 2022). "Malaria is also strongly associated with a hypercoagulopathy condition through activation of the coagulation cascade triggered by proinflammatory cytokines [e.g., tumour necrosis factor (TNF) and interleukin (IL)-6]." (PMID 35739554, 2022). "The null difference in mean IL-6 levels between patients with uncomplicated malaria and those with asymptomatic malaria might be due to Plasmodium spp." (PMID 35396564, 2022). "Taken together, these results indicate that through the induction and expansion of CD11b+Ly6Chi proinflammatory monocytes, the late IL‐6‐mediated immune suppression is a general mechanism that can be used to intervene in infections of different lethal strains of malaria." (PMID 35635376, 2022). "Although IL-6 had been reported to have different roles in the pathogenesis of malaria infection and varies with disease severity, these studies enrolled a limited number of participants with severe malaria and therefore the conclusions are questioned." (PMID 35396564, 2022). "To understand how late IL‐6 dampens anti‐malaria immunity, we considered whether IL‐6 negatively regulates T cell immunity." (PMID 35635376, 2022). "This suggested that a cGAS‐STING‐induced IL‐6 production at day four may play a key role in dampening the anti‐malaria immunity against lethal malaria N67C infections." (PMID 35635376, 2022). "Meta-regression analyses of continents, malarial complications, parasitemia, age, male percentage, malaria diagnostic methods, and IL-6 measurement methods showed that these co-variates did not confound the effect estimate (P > 0.05)." (PMID 35396564, 2022). "Global analysis of lung tissues and BALF of infected mice with MA-ARDS revealed elevated levels of the cytokines and chemokines also reported in the serum of severe malaria in humans mainly, IL-1, IL-6, IL-8, IL-10, TNF-α, IFN-γ, MCP-1/CCL2, MIP-2/CXCL2, IP-10/CXCL10, KC/CXCL1, VEGF, PIGF." (PMID 35677654, 2022). "However, in Malaria patients and co-infected there was a positive correlation between the IL-6 and IL-10 levels (P < 0.0001)." (PMID 35749690, 2022). "Additionally, IL-6 has been linked to severity, where children with CM have increased levels of serum IL-6 compared to those with uncomplicated malaria." (PMID 35250814, 2022). "Following this, we aimed to define the detrimental role of late IL‐6 in anti‐malaria immunity." (PMID 35635376, 2022). "Therefore, in Africa where malaria is endemic, high IL-6 levels are likely a useful marker for determining malaria severity." (PMID 35396564, 2022). "Additionally, to prevent severe malaria, IL-4 and IL-10 can directly downregulate IL-6, TNF-α, and IL-1β." (PMID 35820892, 2022). "Subgroup analysis of Plasmodium species showed higher mean IL-6 levels in patients with uncomplicated malaria than in controls among studies that enrolled patients infected with only P. falciparum (P = 0.008, WMD = 43.86 pg/mL, 95% CI = 11.52–76.2 pg/mL, I2 = 100%, 13 studies)." (PMID 35396564, 2022). "Interestingly for IL-6, in the malaria group the level was 6.9 higher than control (P < 0.0001) and the results showed higher levels of this cytokine compared to all other groups (P < 0.005)." (PMID 35749690, 2022).
malaria (continued). "Similarly, significant elevated level of proinflammatory IL-6 and IL-10 was reported in Malian children with severe-malaria." (PMID 35223394, 2021). "Some investigators have suggested that the balance between pro-inflammatory (TNF-α, IFN-γ, IL-6 and IL-8) and anti-inflammatory (IL-4, IL-10) cytokines determines the degree of malaria parasitaemia, level of anaemia, clinical severity, presentation and outcome." (PMID 34666102, 2021). "IL-27 could be seen as an immunoregulatory cytokine in malaria, having a proinflammatory (induces IL-6 release) as well as an anti-inflammatory (inhibits IL-8 release) role." (PMID 34790829, 2021). "This study aims to evaluate the CD4+ and CD8+ T cells, leucocytes subpopulations, IL-6, IL-10 and biomarkers of oxidative stress among children infected with varying grades of malaria attending the University of Abuja Teaching Hospital and National Hospital, Abuja, Nigeria." (PMID 35223394, 2021). "However, excessive production of pro-inflammatory cytokines such IL-1β, IL-6 and TNF by monocytes/macrophages can result in systemic inflammation that causes fever and other disease manifestations of malaria." (PMID 33822828, 2021). "We previously found in longitudinal analyses of Malian children that Pf-iRBC-inducible production of IL-1β and IL-6 by monocytes was lower 7 days after treatment of febrile malaria relative to that induced at the pre-infection baseline before the six-month malaria season." (PMID 33822828, 2021). "Serum IL-10 and IL-6 significantly elevated with increased malaria density (p<0.0001)." (PMID 35223394, 2021). "Higher levels of proinflammatory cytokines such as interleukin-6 during acute infection in less immune populations and in severe malaria may also contribute through inhibition of cardiomyocyte ion channel function." (PMID 32134952, 2020). "In addition, ex-vivo cytokine production after LPS stimulation was significantly lower for all cytokines, except for IL-6 (p = 0.053), in the asymptomatic malaria infections below the age of 5 years compared to smear-negative healthy subjects." (PMID 33253198, 2020). "Additionally, the mean IL-6 sharply increased in malaria-infected donor blood, peaking at day 21 and then sharply decreased to levels in nonmalaria-infected donor blood." (PMID 33195706, 2020). "Our study estimates that transfusing a 500 mL malaria-infected stored whole blood for 21 days could result in infusing 190 ng, 71.6 ng, or 48.2 ng of IL-6, TNF-α, and IL-12, respectively, to the recipient." (PMID 33195706, 2020). "Pro/anti-inflammatory (IL-6/IL-10) ratio was higher in clinical than asymptomatic malaria." (PMID 33253198, 2020). "Based on our data CXCL10, TNF-α, CCL3, IL-8, and IL-6 may be investigated as potential markers to assess malaria severity and protection." (PMID 33424841, 2020). "IL-6 was reported to be elevated in children with malaria and SCD." (PMID 33424841, 2020). "Circulating CXCL10, CCL3, IL-8, TNF-α, and IL-6 could be used as potential biomarkers for malaria severity among individuals with hemoglobinopathies." (PMID 33424841, 2020). "We observed increased levels of cytokines such as TNF-α and IL-6 in children with microscopic asymptomatic malaria, whereas, IFN-γ, IL-17A, and IL-4 levels were increased in infected children with microscopic or submicroscopic asymptomatic malaria compared with uninfected controls." (PMID 33281757, 2020). "Also, it has been shown that the levels of TNF-α, IL-2, IL-10, IL-6 in Plasmodium-helminth co-infected individuals were significantly higher than the malaria-positive (MP) group dampening the immune response to malaria." (PMID 33170876, 2020). "Also, elevated levels of TGF-β, TNF-α, IL-10, and IL-1β were found in cerebral malaria, while IL-2, IFN-γ, IL-5, IL-6, and IL-12 were only increased in mild malaria." (PMID 31878288, 2019).
malaria (continued). "In a study of malaria infection of children in Mali, severe malaria cases, in comparison with matched healthy controls, showed higher levels of IL-6, IL-10, TNF, IL-12(p70), and IL-6 and IL-10 were higher in severe cases in comparison with matched uncomplicated malaria controls." (PMID 31234875, 2019). "In addition, increased levels of IL-6 and IL-10, and decreased levels of RANTES were detected in 2010; these three cytokines have been associated with severe malaria." (PMID 31806027, 2019). "This shows there is still a need to study the role of IL-6 in severe malaria." (PMID 29034874, 2017). "Quantification of levels of pro-inflammatory cytokines, including TNF-α, IFN-γ, IL-1β, IL-2, IL-8, IL-6, IL-12, and GM-CSF in children with malaria in the three transmission areas revealed a pattern of decreasing cytokine levels with increasing transmission intensity (Accra > Navrongo > Kintampo)." (PMID 28399920, 2017). "TNF-α, IFN-γ, IL-1, IL-6, IL-8, and IL-10 have been found in increased levels in patients with severe malaria compared to healthy controls, decreasing in convalescence to control levels, but in these studies the clinical syndromes of severe malaria were not fully described." (PMID 28122790, 2017). "Regarding the individual biomarkers, we found pro-inflammatory immune mediators increased in malaria patients with levels of IL-6 and IL-8 higher in CM compared to NCM individuals, and of eotaxin, IL-15, MCP-1 and TNFα elevated in deceased compared to survivors of CM." (PMID 27168977, 2016). "Moreover, the recurrent malaria group displayed significantly augmented levels of IL-10, IL-6, and IL-4 as compared to patients with primary malaria (p < 0.0005, p < 0.005 and p < 0.05, respectively)." (PMID 27581163, 2016). "It was proposed that the levels of TNF and IL-6 are indicators of malaria severity." (PMID 27515948, 2016). "In this study, levels of the IL-10, IL-6 and IL-4 were higher in patients with recurrent malaria." (PMID 27581163, 2016). "Inhibition of IL-6 trans-signaling protects from P. chabaudi malaria." (PMID 27471498, 2016). "In this study, we demonstrate that O. volvulus-infected individuals, residing within co-endemic areas of malaria in Ghana, presented increased IL-6, TNF-α and IL-10 production in response to the P. falciparum-derived antigen MSP-1 when compared to uninfected individuals." (PMID 25889652, 2015). "The severity of blood-stage malaria correlates with circulating IL-6 levels." (PMID 25408684, 2014). "A study of sympatric ethnic groups in Mali found that the frequency of IL6 CG/GG genotypes was higher in non-Fulani ethnic groups, who have increased susceptibility to malaria, in both symptomatic and asymptomatic falciparum malaria cases." (PMID 25038626, 2014). "Malaria patients in their turn, display a strong correlation between the levels of IL-6 and IL-10." (PMID 24741587, 2014). "For malaria infected individuals (M and CI) the profile was high levels of IL-1β, IL-6, TNF-α IL-10, and CRP and decreased levels of IL-17A while for malaria negative individuals (IP and UN) the profile was high levels of IL-17A, NO and decreased levels of IL-10 and CRP." (PMID 25309052, 2014). "CRP was adjusted for malaria and bacteremia; IL-6 was adjusted for bacteremia." (PMID 24339866, 2013). "To investigate a potential role for UA in malaria pathogenesis, we first measured the levels of ten cytokines (IL-6, IL-10, MCP-1, sTNFRII, IL-8, IP-10, TNFα, IFNγ, GM-CSF and IL-1β) that other studies have implicated in the development of severe malaria in humans." (PMID 23071567, 2012). "Malaria-free placentas had higher levels of IL-6 in comparison with infected placentas." (PMID 26623293, 2012). "In the uncomplicated malaria group, children with at least one long GTn repeat allele produced the most TNF (p = 0.007), and children homozygous for Δ22 produced the most IL-6 compared to children with other genotypes (p = 0.041)." (PMID 22336003, 2012).
malaria (continued). "Of potential relevance, in this regard, is the observation that the pro-inflammatory cytokine interleukin-6 is elevated in malaria and also implicated in the non-osmotic release of AVP." (PMID 22280539, 2012). "It is certainly interesting to note that the pro-inflammatory cytokine interleukin-6 is elevated in malaria and also implicated in the non-osmotic release of vasopressin." (PMID 20497587, 2010). "As a result, pregnant women with a history of malaria had high levels of all evaluated cytokines when compared to pregnant women without prior exposure to the parasite; this increase was more relevant among the cytokines IL-6, IL-8, IL-10 and TNF-α (respectively)." (PMID 39495782, 2024). "Other studies show that IL-6 acts in concert with TNF-α and other inflammatory mediators in the clearance of malaria parasites but a meta-analysis by Wilairatana, Mala showed that although IL-6 may be a marker of Plasmodium infection, increased levels are associated with hyperparasitaemia." (PMID 38404582, 2024). "Thus, observational studies of human malaria and studies in mice have not proven a causal role for IL-6 in severe malaria in humans, and alternative approaches are needed to address this question." (PMID 36801374, 2023). "Befitting any general immune response mechanism, various cytokines may potentially modulate ICAM1 expression, of which we have found evidence for statistical association of IL1, IL4 (and its receptor, IL4R), IL6, IL13, TLR2, TLR4, and IFNG (and its receptor, IFNGR1) polymorphisms with malaria." (PMID 37287037, 2023). "Therefore, decreased IL-6 levels in patients with malaria and intestinal parasite coinfections might be a protective factor for disease severity among individuals with coinfections." (PMID 36716305, 2023). "Furthermore, levels of IL-6 are elevated in malaria disease and contribute to disease severity." (PMID 36239109, 2022). "The IL-10/IL-6 ratio tended to be higher in those with P. falciparum infections alone (2.0 [0.9–3.6]) and 2-fold (2.5 [1.8–4.7]) and 3-fold (3.6 [2.0–11.9]) higher in those with dual infections with malaria/filariae and malaria/intestinal protozoans, respectively." (PMID 35421083, 2022). "Therefore, it is recommended that future studies should investigate alterations of IL-6 levels in asymptomatic malaria to determine whether the IL-6 levels are altered in patients with asymptomatic malaria." (PMID 35396564, 2022). "Therefore, further studies investigating the role of IL-6 in malaria-related mortality are needed." (PMID 35396564, 2022). "However, elevated levels of proinflammatory cytokines such as TNF-α, IL-6, or IL-8 may be markers of severe malaria." (PMID 34790829, 2021). "IL-6 and IL-8 are proinflammatory cytokines that may be involved in the pathogenesis of malaria." (PMID 34790829, 2021). "We evaluated the expression of CXCL10, TNF-α, CCL2, CCL3, IL-8, and IL-6 among 74 volunteers, from a pool of 923, with one (HbAS and HbAC), two (HbSS, HbSC, HbCC) and no (HbAA) copies of the Hb allele variant S and/or C with (+) and without (-) malaria." (PMID 33424841, 2020). "Interestingly, IFN-γ, IL-6 and IL-13 displayed the highest relative number of network interactions in the group of dengue mono-infected patients, whereas IL-12p70 exhibited the highest relative number of interactions in the malaria mono-infection group." (PMID 26271921, 2015). "However, when these participants developed an acute episode of malaria, IL-6 and IL-10 cytokines increased considerably in all groups, but to a higher extent in subjects who were free of schistosome infection, which would suggest that S. haematobium impedes the cytokine storm." (PMID 25890010, 2015). "Previous studies showed overexpression of pro-inflammatory cytokines TNFα, IL-1α and IL-6 in CM patients promotes pathogenesis of CM (acute immune activation, promotion of adhesion molecules, leukocyte recruitment, fever and BBB disruption) and were associated with severe and lethal malaria." (PMID 24433482, 2014).